DUSP1 (dual specificity phosphatase 1)
Diseases named in the same sentence as DUSP1 in open-access papers (continued):
Sharing a sentence is not in itself a finding about the gene and the disease.
infection (70 papers, 2007 to 2026). The state of being infected such as from the introduction of a foreign agent such as serum, vaccine, antigenic substance or organism. "In young mice, treatment with dexamethasone increased the levels of Dusp1 and Ptprs and their susceptibility to infection." (PMID 38459711, 2024). "In the context of pathogenic infections, the activation of MAPKs induces the expression of innate immune response genes as well as DUSP1, which prevents overreactive immune responses (29, –, 31)." (PMID 36625590, 2023). "Taken together, these results suggest that m6A and YTHDF2 are involved in fine-tuning the expression of the DUSP1 protein, an important regulator of innate immunity, during pathogenic infections." (PMID 36625590, 2023). "DUSP1 expression is enhanced upon numerous pathogenic infections, and it is an important feedback mechanism for controlling excessive immune responses and inflammation." (PMID 36625590, 2023). "Contrary to what we saw for DUSP-1, challenge with L. pneumophila Dot+ led to a significant increase in cell-associated pro-IL-1β levels after 4 hrs of infection." (PMID 25058342, 2014). "DUSP1 appears to be a major feedback regulator of the innate immune response, and to play a critical role in preventing septic shock and multi-organ dysfunction during pathogenic infection." (PMID 19513121, 2009). "DUSP1 KO mice experienced a significant (higher dose, day 3: p<0.005; low dose, day 4: p<0.05) more accelerated weight loss than their wild-type littermates during the course of the infection, with a reduction of 25% (high dose) or 21% (low dose) at day 5 post-infection." (PMID 24244156, 2013). "Further linking age‐associated levels of TNF to heightened levels of these cell signaling suppressors and greater susceptibility to infection, we observed that the treatment of aged mice with anti‐TNF lowered Dusp1 expression eightfold and Ptprs by 50‐fold." (PMID 38459711, 2024). "The IL-1β protein level was also upregulated after DUSP1 knockdown during infections by P. aeruginosa, C. diphtheriae, and the HSV-1 ICP34.5 mutant." (PMID 36625590, 2023). "The objective of this study was therefore to investigate the function of DUSP1 in macrophages after infection with Mtb." (PMID 36788275, 2023). "The DUSP1 transcript m6A level was increased by 2.3-fold 2 h after infection with P. aeruginosa but then decreased at 4 and 6 hpi." (PMID 36625590, 2023). "Both serum IFNβ and hepatic IFNβ-dependent genes (including Ifit2, Rsad2, Iigp1 and many more of the ISGs discussed here) were over-expressed in Dusp1-/- mice following infection with E. coli." (PMID 37942320, 2023). "Taken together, these findings indicated that DUSP1 knockdown combined with BCG-infection model was successful." (PMID 36788275, 2023). "Analysis of scRNA-Seq data and validation by qRT-PCR showed that DUSP1 is upregulated at 1 h, 16 h, and 24 h post-infection reflecting its role in modulating the pro-inflammatory cytokine expression in BMNs during Bb infection." (PMID 38149246, 2023). "Contrary to the SARS-CoV-2 infection, infection with coronavirus infectious bronchitis virus (IBV) resulted in an increase in DUSP1 as viral defense mechanism to reduce p38 MAPK activation and IL-6 and IL-8 cytokine production." (PMID 33995033, 2021). "This was illustrated by the temporal difference in gene expression of the MAPK/ERK pathway during infection and illuminated a critical role for DUSPs, specifically DUSP1, during JCPyV infection in NHAs." (PMID 34578413, 2021). "An important gene for growth during stress, CHORDC1 associated with post-infection growth rate was identified as a positional candidate gene, as well as other immune related genes, including VAV2, IL12B, DUSP1, and IL17B." (PMID 32849779, 2020). "Infection with RV16 increased DUSP1 mRNA expression at 24 h; however, this was variable and nonsignificant." (PMID 30333178, 2019).
infection (continued). "A similar role for DUSP1 was seen in infection of the NCI-H1299 cell line with the avian coronavirus infectious bronchitis virus, with DUSP1 siRNA treatment increasing mRNA levels of CXCL8 in response to infection." (PMID 30764493, 2019). "A549 cells were cotransfected with JIP1 together with empty or DUSP1-expressing constructs before infection with SeV or RSV." (PMID 29234123, 2017). "The observation that JIP1 prevents JNK from being dephosphorylated by DUSP1 suggests a model in which AP-1-dependent functions would be protected from the negative regulation of DUSP1 during the infection." (PMID 29234123, 2017). "Infection of DUSP1 knockout mice with MVA enhanced the production of pro-inflammatory cytokines indicating that DUSP1 is involved in the regulation of innate and adaptive immune responses during poxvirus infection." (PMID 29109380, 2017). "Infection of Hela cells or mouse embryonic fibroblasts (MEFs) with MVA resulted in the upregulation of dual specificity phosphatase 1 (DUSP1), a MAPK dephosphorylating enzyme." (PMID 29109380, 2017). "Collectively, our data unveils a previously unrecognized selective role of DUSP1 in the regulation of tissue damage and repair during infections by RSV and SeV." (PMID 29234123, 2017). "In the presence of MG132, induction of DUSP1 is detectable in both infections and the overall DUSP1 levels were markedly increased compared to control cells." (PMID 29234123, 2017). "Although, there was significantly decreased DUSP1 expression noted in CAMs post infection, an early and sustained relative upregulation of TPL-2 was seen in AAMs (p = 0.03 at 1,4,6 and 24 hours)." (PMID 28658262, 2017). "DUSP1 was induced in epithelial cells ~6 hours post-infection and reached a maximal level after 8 hours following infection with the rim101Δ/Δ mutant." (PMID 27088599, 2016). "This transcriptional response, however, was not accompanied by translation either in bone marrow-derived macrophages or U937 cells as DUSP-1 protein levels remained unchanged over the course of infection." (PMID 25058342, 2014). "Bone marrow-derived macrophages challenged with wild type Legionella for 4 hrs showed significant induction of the Dusp1 transcript compared to dotA3 infection." (PMID 25058342, 2014). "DUSP1 is involved in innate and adaptive immune responses against different bacteria and parasites infections." (PMID 24244156, 2013). "In cultured cells, we have demonstrated that VACV specifically upregulates DUSP1 during infection and this induction is dependent on early viral protein synthesis." (PMID 24244156, 2013). "DUSP1 protein was upregulated during the infection with each one of the three viruses used and this increase peaked between 4 and 6 hpi." (PMID 24244156, 2013). "The highest levels of DUSP1 induction were observed upon NYVAC infection where an increase in protein expression was still detected at 8 hpi." (PMID 24244156, 2013). "The viral titers in the lungs of infected animals at days 2 and 5 post-infection were higher in DUSP1 KO infected mice in comparison with WT mice at both times post-infection." (PMID 24244156, 2013). "We demonstrated that DUSP1 expression is enhanced upon infection with the replicative WR virus and with the attenuated VACV viruses MVA and NYVAC." (PMID 24244156, 2013). "As shown by RT-PCR, in HeLa cells infected with WR, MVA or NYVAC, there was an increase in DUSP1 mRNA levels at the different times post-infection analyzed." (PMID 24244156, 2013). "To further analyze this effect, we first focused on innate immune responses triggered after systemic (i.p) infection of DUSP1 WT and KO mice with 107 PFU/mouse of WR or 2×107 PFU/mouse of MVA or NYVAC." (PMID 24244156, 2013). "Differences in levels and in temporal induction of these cytokines were found between infections with MVA versus NYVAC in DUSP1 KO mice, an expected finding since these two viruses differ in the number of immunomodulatory genes present in their genomes." (PMID 24244156, 2013).
infection (continued). "Here, we have evaluated the role of the MAPK negative regulator dual specificity phosphatase 1 (DUSP1) in the infection of VACV." (PMID 24244156, 2013). "In addition, these infection-induced T cells displayed typical memory markers, including Cd7, and a resting cell signature, reflected by Jun, Fosb, Dusp1, and Dusp2 expression." (PMID 40240341, 2025). "In addition, the release of TNF-α and IL-1β induced by BCG (MOI = 10) infection was reversed by siRNA-DUSP1 transfection, indicating that DUSP1 knockdown inhibited the BCG-induced inflammatory response in THP-1 cells." (PMID 36788275, 2023). "We showed via Western blotting that DUSP1 expression was significantly upregulated after treatment of THP-1 cells with BCG at different multiplicities of infection (MOI) at different time points post-infection." (PMID 36788275, 2023). "However, DUSP1 demonstrated an interesting pattern of reduction in NHAs at 48 hpi and remained lower at 96 hpi, as JCPyV infection progressed." (PMID 34578413, 2021). "Importantly, DUSP1 promotes virus-induced apoptosis and suppresses cell migration in infected cells, hence suggesting a possible role of DUSP1 in the regulation of tissue damage and repair during infection by SARS-CoV-2." (PMID 34073047, 2021). "Genes in these regions, including CHORDC1 and DUSP1 are important candidate genes for post-infection rate and viral load at 2 and 6 dpi, respectively, and could be crucial in the chickens’ response to NDV infection." (PMID 32849779, 2020). "In addition, we have further confirmed this enhanced WR and MVA replication in DUSP1 KO MEFs using specific siRNAs against DUSP1 in WR or MVA infection in cells from different origin such as HeLa cells, and also restoring DUSP1 expression in DUSP1 KO cells." (PMID 24244156, 2013). "Moreover, the onset of mortality of DUSP1 KO mice began as soon as 4 days post-infection, with the death of 3 out of 5 mice and reached the top at 6 days post-infection." (PMID 24244156, 2013). "We observed phosphorylation of DUSP1 after the infection with each one of the three viruses used." (PMID 24244156, 2013). "The promoter region of Dusp1 is tightly regulated and contains binding sites for several transcription factors, including a glucocorticoid receptor, which was taken advantage of in our study to determine the consequence of its upregulation on the AM response to infection." (PMID 38459711, 2024). "Moreover, DUSP1 may also be differentially expressed during coronavirus infection, highlighting the importance of this protein during infection across many viral families." (PMID 34578413, 2021). "Indeed, one can hypothesize that inhibition of the JIP1/JNK interaction might restore DUSP1-dependent inhibition of the AP-1/cytokine axis during the infection, while leaving other JIP1-independent JNK functions unaffected." (PMID 29234123, 2017). "In Bb-infected BMNs, DUSP1 and CLEC4D showed consistent upregulation at 1 h, 16 h, and 24 h post-infection (hpi), while Casp3 was significantly upregulated at 16 hpi and 24 hpi." (PMID 38149246, 2023). "Similar, in the chicken, DUSP1, DUSP5, DUSP7, DUSP10, DUSP15, and DUSP16 were significantly downregulated in response to infection." (PMID 36683094, 2023). "In the present study, we report that infection with BCG significantly induces macrophage apoptosis and induces the production of DUSP1, TNF-α and IL-1β." (PMID 36788275, 2023). "In contrast, WT infection induced significantly higher expressions of genes that negatively regulate type I IFN expression, such as AHR, DUSP1, HES1, and PRDM1, compared to the mutant-infected cells." (PMID 37513744, 2023). "Instead, four IFN expression inhibitory genes (AHR, DUSP1, HES1, and PRDM1) were significantly up-regulated by WT infection." (PMID 37513744, 2023). "The expression of the anti-inflammatory molecules IL-10, ANXA1, DUSP1, GILZ and HO-1 was significantly increased upon infection." (PMID 34843584, 2021).
infection (continued). "One mechanism of its anti-inflammatory effects is increasing the expression and activity of dual specificity phosphatase 1 (DUSP1), an endogenous negative regulator in infection." (PMID 32448150, 2020). "Our RNA-seq analysis shows that several inhibitors of the NF-kB and MAPK signaling pathways were significantly down-regulated 36 days after infection, including NFKBID, NFKBIZ, DUSP-1, -2, NR4A2, and tristetraprolin (TTP or ZFP36)." (PMID 33324683, 2020). "Analysis of mRNA levels for the specific genes (selected ) by qPCR demonstrated that for the genes DUSP1 and EDN1 the changes in mRNA levels following infection were reverted to their preinfection levels following cure." (PMID 31216276, 2019). "DUSP1 was induced by about 4 fold at 6 h of RSV infection and was returned to basal levels at 24 h post-infection." (PMID 29234123, 2017). "Consistent with a previous report, genes in the DUSP family (DUSP1, DUSP2, DUSP5 and DUSP6), which regulate MAPK signaling, were down-regulated at four time points post-infection." (PMID 23527143, 2013). "DUSP1 WT and KO mice were i.p. inoculated with WR (107 PFU/mouse), MVA or NYVAC (2×107 PFU/mouse) and animals sacrificed after 10 days post-infection." (PMID 24244156, 2013). "The MAPKs inhibitors were added to DUSP1 KO cells, previously infected with MVA, at 0, 1 or 3 hours post-infection and 24 hours later viral titers were determined." (PMID 24244156, 2013). "Among them, DUSP1, an important regulator of innate immune response genes, was significantly hypermethylated during infection with the Gram-negative bacterium Pseudomonas aeruginosa, which peaked at 2 h postinfection (hpi) and then decreased at 4 and 6 hpi." (PMID 36625590, 2023). "This was supported by the upregulation of the NF-kB inhibitor genes NFKBIA and NFKBIZ, the AP-1 transcription factor complex genes FOS, JUN, FOSB and JUNB as well as other NF-kB target genes such as TNFAIP3, RELB, NR4A2, DUSP1 and CD69 in response to infection." (PMID 37700317, 2023). "Similarly, infections with human respiratory syncytial virus (RSV) and Sendai virus (SeV) upregulated DUSP1 expression and negatively regulated p38 MAPK." (PMID 33995033, 2021). "Interestingly, infection with SARS-CoV-2 resulted in lower expression level of DUSPs, including DUSP1 and DUSP5 in infected AEC as compared to SARS-CoV-1 and MERS-CoV." (PMID 33995033, 2021). "DUSP1 knockdown significantly reduced JCPyV infection in NHAs yet had no impact on infection in SVGAs or NHA-Ts." (PMID 34578413, 2021). "Using two mouse infection models, the Listeria monocytogenes (Th1 biased model) and Candida albicans (Th17 biased model), they found that dendritic cells lacking DUSP1/MKP-1 exhibited reduced IL-12 production and attenuated IFNγ expression and Th1 responses." (PMID 30401534, 2019). "L. rhamnosus colonization alone or combined with C. albicans infection resulted in a marginal induction of cFOS, DUSP1, DUSP5 and NFKBIA expression at early time points, but L. rhamnosus colonization before infection downregulated these genes at later stages of infection." (PMID 31413153, 2019). "Expression of DUSP1 and DUSP4 was unaltered by infection with RV1B." (PMID 30333178, 2019). "In contrast to SeV, RSV does not induce significant apoptosis at early time of infection (63 and data not shown) when DUSP1 dephosphorylates JNK/p38." (PMID 29234123, 2017). "DUSP1, IL-24, and DUSP6 were induced 2–3 hours post-infection with the high dose of wild-type C. albicans and reached a maximal level of induction ~6 hours post-infection." (PMID 27088599, 2016). "Significantly, MVA, which is known to produce non-permissive infections in most mammalian cell lines, is able to grow in DUSP1 KO immortalized murine embryo fibroblasts (MEFs)." (PMID 24244156, 2013).
infection (continued). "Infections by the i.n. route revealed also significant differences (p<0.001) in the magnitude and polyfunctionality of the E3-specific CD8 T cell responses between the three viruses, particularly for DUSP1 KO infected animals." (PMID 24244156, 2013). "To address this issue, we infected DUSP1 WT and KO MEFs with WR, MVA or NYVAC at 5 PFU/cell and analyzed the expression of these proteins by Western-blot at 0.25, 0.5, 1, 2, 4, 6 and 8 hours post-infection." (PMID 24244156, 2013). "Results from DUSP1 siRNA elucidated other mechanisms or pathways JCPyV may modulate during infection of NHAs, not observed in SVGAs and NHA-Ts." (PMID 34578413, 2021). "Then, the phosphorylation status of viral structural proteins may be affected by the absence of DUSP1 during MVA infection and this may have an effect on virus morphogenesis." (PMID 24244156, 2013). "In addition, we evaluated MVA and NYVAC infection of mice in the absence of DUSP1 administered by different routes of inoculation." (PMID 24244156, 2013). "Thus, the MAPK-mediated hyper-phosphorylation in the absence of DUSP1 during MVA infection may be miss-regulating these processes in a manner that MVA is able to replicate in murine cells." (PMID 24244156, 2013). "We found three genes that were commonly activated with infection with SCV2 at both 12 and 24 hpi (DUSP1, HES1, KLF2) and some non-congruent genes at 12 hpi (CCL5, ZBP1, NRXN2, STAB1, SLC25A47, CXCL11) and 24 hpi (FOXA2, RHOB)." (PMID 37504520, 2023). "Productive MVA infection required DUSP1 KO MEF immortalization process, as MVA produced abortive infections in primary DUSP1 KO MEFs obtained from DUSP1 KO mice (data not shown)." (PMID 24244156, 2013).
metabolic disease (11 papers, 2010 to 2024). A congenital disorder (due to inherited enzyme abnormality) or acquired (due to failure of a metabolically important organ) disorder resulting from an abnormal metabolic process. "Metabolic disorder-induced oxidative stress causes DUSP1 S-glutathionylation and subsequent proteasomal degradation of DUSP1, resulting in monocyte migration and macrophage recruitment." (PMID 31151270, 2019).
bacterial infection (8 papers, 2013 to 2023). "Importantly, YTHDF2 was significantly induced during bacterial infections, which maximized its negative regulation of DUSP1 transcript stability." (PMID 36625590, 2023). "Here, we report that in response to viral and bacterial infections, not only the DUSP1 transcript but also its N6-methyladenosine (m6A) levels rapidly increase together with that of the m6A reader protein YTHDF2, resulting in enhanced YTHDF2-mediated DUSP1 transcript degradation." (PMID 36625590, 2023). "m6A mediates DUSP1 transcript expression during bacterial infection." (PMID 36625590, 2023). "Although 94 predicted upstream regulators were conserved amongst the studies, 14 were found only in the endometrium of pregnant healthy cows, and 5 were found only in cows following bacterial infection, including AIRE, NFKBIA, and DUSP1." (PMID 35358206, 2022).
neurodegenerative disease (5 papers, 2011 to 2022). A disorder of the central nervous system characterized by gradual and progressive loss of neural tissue and neurologic function. "In mice Dusp1 has been shown to play a neuroprotective role in a variety of neurodegenerative disease and Dusp1-/- mice exhibit defects in neurogenesis." (PMID 35999349, 2022). "It is not surprising to find striking changes in the expression levels and activity of these phosphatases in neurodegenerative diseases, as occurs with the downregulation of DUSP1 and DUSP6 in AD and HD." (PMID 31018603, 2019).
neurological disorders (4 papers, 2021 to 2025). "Neuroprotective roles have previously been ascribed to DUSP1, and reduced levels have been related to neurological disorders." (PMID 34572983, 2021).
immune disorder (3 papers, 2021 to 2025). "Thus, DUSP1 influences the activity of immune cells and the process of fibrosis in tissues by regulating MAPK, and it has therefore become a potential therapeutic target in some immune diseases." (PMID 36250071, 2022).